ALB (albumin)
Diseases named in the same sentence as ALB in open-access papers (continued):
Sharing a sentence is not in itself a finding about the gene and the disease.
Hyperkalemia (40 papers, 2010 to 2026). An abnormally increased potassium concentration in the blood. "Combination therapy with SGLT2i and nsMRA not only achieved greater reduction in urine albumin creatinine ratio (uACR) compared to either monotherapy but also demonstrated a lower risk of hyperkalemia than monotherapy with nsMRA." (PMID 41464819, 2025). "In clinical trials, the combination of MRA and ACEI/ARB significantly reduced urinary albumin excretion and urinary albumin-creatinine ratio and significantly increased the risk of hyperkalemia." (PMID 36304156, 2022). "This meta-analysis confirms that MRA use in combination with ACE-I and/or ARB is associated with significant reductions in BP and end-of-treatment protein/albumin excretion, while conferring a small and quantifiable increased risk of hyperkalaemia." (PMID 27609359, 2016). "Mineralocorticoid receptor antagonism reduced weighted mean protein/albumin excretion by 38.7 % but with a threefold higher relative risk of withdrawing from the trial due to hyperkalaemia (3.21, [1.19, 8.71])." (PMID 27609359, 2016). "Mineralocorticoid receptor antagonism reduces blood pressure and urinary protein/albumin excretion with a quantifiable risk of hyperkalaemia above predefined study upper limit." (PMID 27609359, 2016). "This suggests that patients are able to understand and utilize the EP-10 to meet their recommended protein intake and achieve an improvement in their albumin level yet avoid the associated complications of hyperphosphatemia and hyperkalemia." (PMID 24967248, 2013). "In general, individuals with hyperkalemia exhibited lower body temperatures, blood pressures, blood oxygen levels, hemoglobin concentrations, platelet counts, albumin levels and so forth." (PMID 38824546, 2024). "Several meta-analyses on steroidal MRAs in diabetic CKD reported an improvement in urinary albumin–creatinine ratio (UACR) but with a dramatic increased incidence of hyperkalemia." (PMID 37373685, 2023). "Degenerative left shift, hypernatremia, hyperkalemia, hypochloridemia, and hyperproteinemia with low albumin-to-globulin ratios were other hemato-biochemical features reported in A. platys + T." (PMID 34275459, 2021). "Several other baseline characteristics did not appear balanced between the study groups with more patients in the albumin group initiated on SLED for hyperkalemia." (PMID 34902089, 2021). "Prolonged anesthesia time, preoperative albumin, and intraoperative blood transfusion were independent risks factors in the development of hyperkalemia." (PMID 32477508, 2020). "We focused on change in urinary protein/albumin excretion, progression of CKD and risk of hyperkalaemia whilst additionally collecting hard clinical endpoints where these data were available." (PMID 27609359, 2016). "The fully adjusted Model 3 identified four independent predictors: higher Killip class III/IV (OR = 2.99, 95% CI 1.61–5.56), elevated neutrophil percentage (OR = 1.05, 95% CI 1.02–1.08), hyperkalemia (K+: OR = 1.70, 95% CI 1.08–2.70), and lower serum albumin (ALB: OR = 0.92, 95% CI 0.87–0.97)." (PMID 41409354, 2025). "Hyperkalemia was also more prevalent in participants with serum albumin less than 2.5 mg/dL (65.3% vs. 34.6%; p-value: <0.0001) Similarly, hyperkalemia was more prevalent in participants with serum bilirubin more than 2.8 mg/dL (68.3% vs. 31.7%; p-value: 0.001)." (PMID 34725608, 2021). "The group with a possible risk of hyperkalemia (potassium-sparing diuretics users), however, was not separately investigated in subgroups by urinary albumin." (PMID 31375970, 2019). "The secondary endpoints are incidence of hyperkalaemia, change in estimated glomerular filtration rate, change in urine albumin:creatinine ratio, change in brachial blood pressure, change in pulse waveform characteristics and overall tolerability of spironolactone." (PMID 24886272, 2014).
Hyperkalemia (continued). "Hyperkalemia occurred more frequently in older patients with a higher white blood cell (WBC) count, serum creatinine level, BUN, MELD score, and CLIF-SOFA score (P<0.001) and lower mean arterial pressure, serum sodium and albumin levels (P<0.05)." (PMID 30937312, 2019). "ACEI in combination with ARB was more effective in reducing urine albumin excretion and urine protein excretion than high-dose ACEI or ARB, without decreased GFR and increased rate of hyperkalemia." (PMID 34025408, 2021).
neuropathy (40 papers, 2010 to 2026). A disorder affecting the nervous system that manifests with pain, tingling, numbness, and/or muscle weakness. "Recently, high IL-6, lower serum albumin, more severe neuropathy and ascites were identified as factors associated with development of calciphylaxis in POEMS patients." (PMID 38435320, 2024). "Among POEMS patients, higher disease activity, including more severe neuropathy and ascites, higher serum levels of interleukin-6, and lower serum albumin levels, was associated with the development of calciphylaxis." (PMID 27068711, 2016). "Multivariate regression analysis identified predictors that were significantly associated with worsening neuropathy based on Total Neuropathy Score (TNS) included low serum albumin (p = 0.002), paclitaxel dose (p = 0.001), and increased body surface area (p = 0.006)." (PMID 35054049, 2022). "Many uses of albumin-bound paclitaxel in clinical studies were only evaluated for 30 min infusions, which could be the cause of the increased numbers of neuropathy, when observed." (PMID 33503889, 2021). "Our patient had evidence of cytokine dysregulation, including high VEGF and IL-6, neuropathy, low albumin, and severe ascites." (PMID 38435320, 2024). "The highest grade of neuropathy reported during chemotherapy was used and glucose, hemoglobin, albumin, and potassium data from before chemotherapy initiation were used." (PMID 35054049, 2022). "It was also found that administering albumin-bound paclitaxel over a short period of time, when compared among 1 h versus 3 h or 3 h versus 24 h, generally increased neuropathy adverse events." (PMID 33503889, 2021). "The results were similar except that improvement in toe tuning fork vibration and tendon reflex score is attenuated in patients with urine albumin–creatinine > 30 mg/g and those with Michigan Neuropathy Screening Instrument Score > 2.5 points at baseline." (PMID 32683637, 2021). "Our study found nocorrelation between BMI, serum albumin, or B12 levels and neuropathy, which may be due to limitations in sample size." (PMID 41393484, 2025). "Reduced albumin levels are indicative of poor nutritional status and systemic inflammation, both of which negatively affect neural repair mechanisms and contribute to worsening neuropathy." (PMID 39744304, 2024). "This takes approximately 20 min, and this time is used to carry out anthropometric measurements (weight and waist‐hip ratio), blood pressure, blood tests (HbA1c, lipid profile, urea and electrolytes), urine test for urinary albumin excretion rate, smoking assessment and foot/neuropathy review." (PMID 39037334, 2024). "Possible explanations for the presence of albumin-cytological dissociation include intrathecal production and release of proteins such as IgG or MBP or neuropathy-induced dysfunction of the blood-nerve barrier." (PMID 38915835, 2024). "The correlation we found between the albumin ratio (QAlb) and the severity of the neuropathy may indicate that patients with a moderate to severe B-CSF barrier dysfunction also present more severe neuropathy and thus, more neurodegeneration, explaining the higher levels of NFL in these patients." (PMID 36860843, 2023). "The urinary albumin to creatinine ratio (ACR), estimated glomerular filtration rate (eGFR) every 3 months and neuropathy outcome measures and mean Z-score of 8 neurophysiological tests were determined at the baseline and endpoint." (PMID 35784562, 2022). "However, a prior study suggested an increased prevalence of neuropathy in patients with lower GFR and higher creatinine and albumin levels." (PMID 41289277, 2025). "Following detailed evaluation of seven articles, the odds ratios of 28 variables were identified, of which nine were acknowledged as the strongest predictors of amputations: elevated WCC, low Hb, low albumin, high CRP and ESR, PAD, neuropathy, osteomyelitis, and Wagner grade >3." (PMID 36035032, 2022).
neuropathy (continued). "She completed the five planned nanoparticle albumin-bound paclitaxel cycles with acceptable tolerability (including persistent grade 2 neuropathy) and without dose delay or adjustments." (PMID 24386978, 2014).
cognitive decline (39 papers, 2014 to 2026). "Other fluid markers of the BBB, including albumin quotient and imaging markers, such as enhanced MRI, have also been associated with cognitive decline." (PMID 40239464, 2025). "It is worth noting that low levels of serum albumin are associated with a state of chronic inflammation, which is an important factor in cognitive decline." (PMID 39262164, 2024). "Previous studies showed that low albumin was an independent risk marker for cognitive decline in older adults." (PMID 35265656, 2022). "Several epidemiological studies have reported that serum albumin and HbA1c are associated with cognitive decline in the elderly." (PMID 34069601, 2021). "RAR, as a composite marker of RDW and albumin, may reflect underlying systemic inflammation, oxidative stress, and poor nutritional status—factors that have been independently associated with cognitive decline." (PMID 40568468, 2025). "Low levels of serum albumin have been associated with brain atrophy, neuronal damage, and neuroinflammation, all of which are important biological mechanisms for cognitive decline." (PMID 39262164, 2024). "In addition, a cohort study in the United States also noted that serum albumin identifies individuals with Parkinson's disease who are at risk for cognitive decline." (PMID 39262164, 2024). "Higher serum levels of vitamin A, vitamin D, TTR, albumin, Se, and UA could act as protective factors against cognitive decline, whereas higher BMI could act as a risk factor." (PMID 35686024, 2022). "The benefit of EAHE in reducing cognitive decline may be associated with improved blood biomarkers such as calcium, albumin, Hb, Hcy, SOD, BDNF, APOE4, and α-ACT, as well as reduced structural deterioration in the ARC and PHC regions of patients with mild AD." (PMID 32581767, 2020). "Finally, two large Japanese cohort studies of older adults concluded that baseline serum albumin and baseline measures of iron status (e.g., hemoglobin) were independently associated with cognitive decline over varying follow-up periods." (PMID 30356710, 2018). "For instance, one study found a significant slowing of cognitive decline (p < 0.05) among patients receiving PE with albumin replacement." (PMID 39421573, 2024). "Subsequent research confirmed these cross-sectional findings, indicating a more significant cognitive decline over a 2-year follow-up period in older individuals with low serum albumin levels." (PMID 39114530, 2024). "Considering the 10 variables with greater feature values (Y axis), higher triglycerides, RDW, albumin, and creatinine levels, as well as lower glucose, hematocrit, hemoglobin, globulin, HDL, and TSH levels are associated with cognitive decline." (PMID 37190655, 2023). "Their subsequent study confirmed these cross-sectional findings and showed a greater cognitive decline over a two-year follow-up in elderly subjects with lower serum albumin levels." (PMID 35160273, 2022). "Evidence suggested that serum albumin can combine with amyloid-β and can reduce its neurotoxicity by inhibiting its aggregation and fibrosis, thus preventing further progression of cognitive decline." (PMID 34880747, 2021). "We demonstrated that severity of cognitive decline was correlated with eGFR, serum albumin, and hemoglobin in the oldest old patients diagnosed with probable AD." (PMID 33028210, 2020). "As cognitive decline proved to be common in patients with CKD and correlated with urinary albumin loss, we may hypothesize that albuminuria may serve as a biomarker for cognition." (PMID 40565866, 2025). "Thus, older patients with low albumin need timely cognitive assessment and intervention for cognitive decline." (PMID 38409895, 2024). "Moreover, evidence suggests that serum albumin can bind to amyloid‐β, attenuating its neurotoxicity and preventing cognitive decline by reducing its aggregation." (PMID 38409895, 2024).
cognitive decline (continued). "The routine laboratory variables, albumin and globulin respectively, could predict cognitive decline through a machine learning algorithm study for those aged ≥75 years." (PMID 38737864, 2024). "Maintaining albumin-to-globulin ratio with an appropriate range may be one of the therapeutic strategies to limit the progression of cognitive decline for the older people." (PMID 38737864, 2024). "Furthermore, recent reports have highlighted the association between poor nutritional status, frailty, lower albumin level, and cognitive decline, emphasizing these as modifiable elements of interest." (PMID 39114530, 2024). "We observed that individuals carrying the ε4 allele were at greater risk of average cognitive decline associated with average low albumin levels than those not carrying the ε4 allele." (PMID 35160273, 2022). "Higher serum albumin (OR per standard deviation (SD) = 0.81, 95% CI: 0.95–0.98), higher DSST score (OR per SD: 0.57, 95% CI: 0.48–0.68), and faster 400 m walk (OR per SD 0.81, 95% CI: 0.68–0.96) were significantly associated with lower odds of cognitive decline." (PMID 36891556, 2023). "Univariate Cox regression analyses revealed that visual impairment, an older age, female sex, not living alone, single marriage status, low education, no drinking, underweight, abnormal TG level and abnormal albumin level increased the risk of cognitive decline (p < 0.0001)." (PMID 34475488, 2021). "Individuals with AD showed evidence of kidney function impairment through higher mean concentrations of total protein, albumin, and UACR compared to controls, consistent with the higher level of albuminuria recognized with cognitive decline." (PMID 32298384, 2020). "Low serum albumin levels acting as a negative acute phase reactant, reflect decreased liver function in the elderly and predispose to decreased antioxidant levels which may accelerate cognitive decline in this population." (PMID 30356710, 2018). "High CRP, low albumin and high ESR each had a specific link to cognitive decline for specific groups within this urban adult population." (PMID 30356710, 2018). "The eighth study showed increased BBB dysfunction in the form of an increased CSF/serum albumin ratio in patients with cognitive decline with CMBs (n = 15) compared with patients with cognitive decline but no CMBs (n = 13)." (PMID 30483207, 2018). "Recently, an RCT performed in patients with mild to moderate AD has shown that plasmapheresis with albumin replacement, with or without the addition of IVIG (to replace endogenous Ig removed by the plasmapheresis), is associated with less functional and cognitive decline." (PMID 36123443, 2023). "However, lower albumin levels did not play an important role in cognitive decline since higher levels were observed in the model after one year of follow up." (PMID 37190655, 2023). "However, intravenous administration of human albumin at a dose of 10 g every 2 weeks in patients with mild or moderate AD did not significantly reduce the cognitive decline as measured by the MMSE and ADAS-cog at 28 weeks." (PMID 33013289, 2020).
colitis (39 papers, 2012 to 2025). Inflammation of the colon. "High dose vitamin D supplementation led to more severe DSS colitis as measured by blinded endoscopic and histologic assessment, weight loss and fall in serum albumin." (PMID 30065252, 2018). "Previous factors associated with higher morbidity and mortality from C-Diff colitis include low serum albumin, intensive care unit admission, older age, and poor immunologic response to toxins released by the bacteria." (PMID 23611947, 2012). "The underlying mechanism of pea albumin in protecting against colitis was investigated." (PMID 36079868, 2022). "The group on high dose vitamin D (D++) developed the most severe colitis as measured by blinded endoscopic (p < 0.001) and histologic (p < 0.05) assessment, weight loss (p < 0.001), drop in serum albumin (p = 0.05) and increased expression of colonic TNF-α (p < 0.05)." (PMID 30065252, 2018). "However, colitis symptoms such as weight loss and faecal albumin were comparable between control and Il6rαKO mice under NCD and HFD conditions, which might be a consequence of the mild HFD-adapted CAC protocol applied here." (PMID 29695802, 2018). "Kidney weight and kidney Il‐1β correlated with the main markers of colitis, e.g., and histopathological scores, colon length, fecal albumin." (PMID 40018982, 2025). "Albumin synthesis has been found to be increased in macronutrient-restricted pigs undergoing colitis." (PMID 41302034, 2025). "AEEL administration improved bodyweight change, colon shortening, MPO activity, and the albumin content of serum in mice with DSS-induced colitis." (PMID 38612870, 2024). "By using 3D bioprinting, we generated a colitis-like condition model that can evaluate the barrier function of albumin nanoencapsulated anti-inflammatory drugs." (PMID 36810372, 2023). "Transient alterations of BBB permeability were also observed in TNBS-induced colitis showing enhanced permeation of Evans Blue-albumin after 1 day and a normalization at later time points." (PMID 36232412, 2022). "Further studies are necessary to understand the contribution of different components of pea albumin in colitis alleviation." (PMID 36079868, 2022). "Horses receiving a course of NSAIDs should ideally have serum albumin or protein concentrations measured weekly for early detection of gastro-intestinal adverse effects, such as right dorsal colitis." (PMID 36359062, 2022). "In the present study, a protective role of pea albumin against DSS-induced colitis, a well-known model for IBD, was investigated." (PMID 36079868, 2022). "Oxidative stress is an important feature of colitis, and studies have shown that colitis can significantly reduce albumin and increase oxidized albumin." (PMID 36590401, 2022). "Albumin level was significantly related to extensive colitis/E3 in UC (P = .026), whereas in CD, it was related to the ileocolonic/L3 location of the disease (P = .005)." (PMID 36086782, 2022). "In the present study, mice supplemented with different doses of pea albumin by oral gavage were subjected to a 2% DSS solution to induce acute colitis." (PMID 36079868, 2022). "In this study, the PRE, PRO, and SYN groups improved body weight change, serum albumin content, and colon length in colitis mice." (PMID 36613533, 2022). "In conclusion, we found that pea albumin administration by oral gavage mitigated DSS-induced colitis." (PMID 36079868, 2022). "Mannose-treated colitis mice exhibited higher levels of serum albumin and lower levels of fecal α1-antitrypsin than the colitis mice." (PMID 35974017, 2022). "Consumption of PRE, PRO, and SYN ameliorated colitis symptoms in body weight, large intestinal length, and serum albumin level." (PMID 36613533, 2022). "As a result, the colitis model mice that received the tacrolimus-albumin complex-encapsulated liposomes showed a slightly decreased loss of weight and colon inflammation compared to saline-treated colitis model mice." (PMID 33810483, 2021).